CD47 (CD47 molecule)
Diseases named in the same sentence as CD47 in open-access papers (continued):
Sharing a sentence is not in itself a finding about the gene and the disease.
tumor (continued). "In pursuit of strategies to specially disrupt the CD47/αvβ3 interaction, we delved into the biophysical mechanisms governing the presence of this complex on tumor cells." (PMID 41168993, 2026). "The average ratio of αvβ3+/CD47+ cells in all normal or paracancerous tissues was 0.23 ± 0.25 (n = 32), significantly lower than the proportion of αvβ3+/CD47+ cells in tumor parenchymal cells (0.61 ± 0.33, n = 119, p < 0.01, Student's t‐test)." (PMID 41168993, 2026). "The SIRPα–CD47 axis is already being targeted clinically to enhance macrophage-mediated tumor clearance." (PMID 41233145, 2026). "We performed IHC staining to evaluate the expression of CD47 and SIRPα in resected tumor tissues from 100 patients who underwent esophagectomy for ESCC." (PMID 40926176, 2026). "Concurrently, the nanoliposomes carry the CRISPR-Cas9 plasmid to knock down the CD47 gene of tumor cells." (PMID 41328345, 2026). "In the 4MOSC1 syngeneic HPV-negative HNSCC mouse model, ALX301 (an engineered CD47-blocking SIRPα fusion for murine models) induced complete tumor regression when combined with anti-PD-1, and produced a partial tumor response as a monotherapy." (PMID 41701713, 2026). "This synergistic effect underscores the central importance of the CD47-SIRPα axis in shaping the immunosuppressive tumor microenvironment." (PMID 40926176, 2026). "Second, approximately 75% of the patients received neoadjuvant treatment in this study; therefore, potentially altering the tumor immune microenvironment and affecting the expression levels of SIRPα and CD47." (PMID 40926176, 2026). "Collectively, these findings demonstrate that GV1001 functions as a potent immunomodulatory anticancer peptide that downregulates CD47 expression and restores macrophage-mediated tumor clearance, highlighting its potential as a therapeutic strategy for OSCC." (PMID 41977514, 2026). "The SIRPα-CD47 "don't eat me" checkpoint axis plays a critical role in shaping antitumor activities of macrophages within the tumor microenvironment (TME)." (PMID 42291136, 2026). "This comprehensive computational approach yields critical structural insights into the interaction between macrophage SIRPα and the tumor cell CD47 immune checkpoint, elucidating the role of αvβ3 in stabilizing CD47 distribution on the cell membrane." (PMID 41168993, 2026). "Blocking the CD47–SIRPα axis can enhance phagocytosis and T cell activity, thereby delaying tumor progression." (PMID 41614894, 2026). "This study aimed to evaluate the impact of tumor localization on systemic inflammatory markers and to investigate CD47 expression in DT." (PMID 42278926, 2026). "In conclusion, this study delineates a mechanistic framework in which integrin αvβ3 and the CD47–SIRPα immune checkpoint engage in reciprocal stabilization at the plasma membrane of tumor cells, thereby potentiating immune escape." (PMID 41168993, 2026). "Overall, these findings demonstrated that up-regulation of STAT3 and CD47 contributed to the evasion of tumour cells from macrophage-mediated phagocytosis." (PMID 41438583, 2026). "Blocking CD47-SIRPα signaling restores reactive oxygen species (ROS) production and antigen presentation in MDSCs, thereby improving anti-tumor immunity." (PMID 41486149, 2026). "CD47 is a key innate immune checkpoint that enables tumor cells to evade macrophage-mediated clearance." (PMID 41601654, 2026). "CD47 is a critical innate immune checkpoint that enables tumor cells to evade macrophage-mediated phagocytosis, and its overexpression is a well-established mechanism of immune escape across multiple cancer types." (PMID 41601654, 2026). "In vivo, oral MCT-NE#9 suppressed tumor growth by 50.4%, with enhanced efficacy (70.3% inhibition) when combined with anti-CD47 therapy." (PMID 41510171, 2026). "One such target is CD47, a macrophage checkpoint protein commonly expressed on tumor cells, that serves as a “don’t-eat-me” signal for macrophage-mediated phagocytosis." (PMID 41484790, 2026).
tumor (continued). "Our analysis of protein expression in clinical tumor tissues reveals a significantly higher proportion of integrin αvβ3 and CD47 double‐positive cells compared to normal tissues." (PMID 41168993, 2026). "In recent years, the CD47-SIRPα pathway has been shown to play a crucial role in immune evasion and tumor progression in various cancers, including laryngeal squamous cell carcinoma, non-small cell lung cancer, rectal cancer, and acute myeloid leukemia." (PMID 40926176, 2026). "CD47 is best known for its role in tumor immune evasion; however, studies in diverse cell models indicate that it also has cell autonomous, tumor-promoting functions which are cell type- and context-specific." (PMID 42007973, 2026). "Additional strategies, including oncolytic viruses and macrophage-specific checkpoint blockade (e.g., CD47/SIRPα axis inhibitors), simultaneously promote tumor clearance and immune activation." (PMID 41924264, 2026). "In the study, CD47 expression was analyzed in both tumor cells (CD47tumor_score) and the TME (CD47micro_score) of CHL patients." (PMID 41811881, 2026). "Here, we introduce a novel mechanism wherein integrin αvβ3 and the CD47–SIRPα axis stabilize each other on tumor cell surfaces, enhancing tumor immune evasion." (PMID 41168993, 2026). "SIRPα, an inhibitory receptor highly expressed on myeloid cells, binds to CD47, a "don't eat me" signal expressed on tumor cells, to inhibit phagocytosis and enable immune evasion." (PMID 41486149, 2026). "Immune checkpoint blockade of CD47 has shown promising results in lymphoid malignancies, with its effects attributed to enabling tumor-cell phagocytosis." (PMID 41484790, 2026). "Together, these findings indicate that DNAJC13 contributes to tumor immune evasion through regulation of CD47 surface abundance." (PMID 41601654, 2026). "A significant positive association between CD47 and MAPK/EMT expression signatures was also evident in large cohorts of NSCLC cell lines and tumor tissues." (PMID 42007973, 2026). "TGF-β and PGE2 further inhibit macrophage activation and interfere with CD47–SIRPα signalling, hindering tumour cell phagocytosis." (PMID 41559435, 2026). "In vivo, HDAC6 blockade also remodels the myeloid compartment (promoting M1-like polarization) and enhances CD8+ T-cell infiltration, creating synergy with anti-CD47 in tumor growth control." (PMID 41486149, 2026). "This action blocks the “don't eat me” signal (the CD47-SIRPα pathway), thereby activating the phagocytosis of macrophages and reducing the characteristics of tumor stem cells to inhibit tumor recurrence." (PMID 41328345, 2026). "We found that CD47 expression is associated with poor prognosis in HNSCC and explored the anti-tumor activity of an anti-CD47 fusion protein in combination with anti-PD1 and lymphatic-sparing radiotherapy in a locally advanced HNSCC model." (PMID 41701713, 2026). "Tumor B7-H3 and CD47 expression was assessed using immunohistochemistry and an immunoreactivity score (IRS); patients were categorized as having negative/low (IRS < 4) or high (IRS ≥ 4) expression." (PMID 42196785, 2026). "Combining ISV of P1 with a CD47 inhibitor SIRPαFc fusion protein showed potent distant tumor suppression effects." (PMID 40733687, 2025). "This lactate-activated epigenetic reprogramming subsequently leads to CD47 upregulation, which in turn inhibits microglia/macrophage phagocytosis and supports tumor cell immune escape via pathways such as STAT3." (PMID 41463052, 2025). "Ongoing phase I trials are exploring bispecific antibodies and combination therapies targeting the SIRPα-CD47 interaction to bolster anti-tumor immunity." (PMID 40070841, 2025). "Given its capacity to regulate immune responses and foster tumor aggressiveness, CD47 is a pivotal factor in cancer progression." (PMID 40765033, 2025).
tumor (continued). "Blocking the SIRPα–CD47 axis can enhance myeloid cell-mediated anti-tumor responses and stimulate adaptive immunity, thereby synergizing with therapeutic antibodies and T-cell checkpoint inhibitors." (PMID 40589735, 2025). "The expression of CD45 in CTCs is consistent with that in corresponding tumor tissues, while CD47 expression is significantly upregulated and closely associated with immune evasion by cancer cells." (PMID 40547026, 2025). "Ectopic expression of Cd47 effectively reversed Smyd3 knockdown‐mediated tumor growth inhibition in an orthotopic syngeneic mouse model." (PMID 40548645, 2025). "CD47 binds to the SIRPα receptor on macrophages, inhibiting macrophage phagocytosis and preventing the immune system from clearing tumor cells." (PMID 40429702, 2025). "The binding of CD47 to SIRPα on macrophages sends a “don't eat me” signal, thereby suppressing the phagocytic activity of these immune cells and allowing tumor cells to evade immune response." (PMID 40385528, 2025). "The immune checkpoint molecule cluster of differentiation 47 (CD47), often described as the “don’t eat me” signal, has gained increasing attention for its role in promoting tumor immune evasion." (PMID 41179296, 2025). "An injectable hydrogel “drug reservoir” device was created to deliver CD47 antibodies and macrophage-targeted altered nanocarriers (pCAR-NPs) in a “filled form” to the postoperative tumor cavity of GBM." (PMID 40230883, 2025). "Currently, the humanized CD47 monoclonal antibody (magrolimab) has shown significant tumor volume reduction in patients with relapsed/refractory lymphoma and has received FDA breakthrough therapy designation." (PMID 40821806, 2025). "The CD47 protein binds to macrophage surfaces via the SIRPα receptor, transmitting a "don't eat me" signal that inhibits macrophage phagocytosis of tumor cells, enabling immune evasion." (PMID 39781344, 2025). "Tumor cells exploit similar evasion strategies by overexpressing these inhibitory signals (e.g., CD47, CD24) or reprogramming macrophages toward pro-tumoral phenotypes via tumor microenvironment (TME) remodeling." (PMID 40380196, 2025). "CD47 is commonly overexpressed on PDAC tumor cells and interacts with SIRPα on macrophages, transmitting a potent “don’t eat me” signal that inhibits phagocytosis and suppresses subsequent antigen presentation." (PMID 41341574, 2025). "In PDAC, CD68+ tumor-infiltrating macrophages play a crucial role in expressing CD47, and their number correlates with the clinical features of PDAC patients and OS." (PMID 40427098, 2025). "They found that CD47 was mainly localized on tumor cell membranes (detected in 250 of 468 cases, 53.4%), with low expression in the stroma and normal mucosa." (PMID 41514569, 2025). "This was previously discussed in the context of rewiring of the TME by cytokines such as IL-12, as well as the strategy of blocking CD47 to promote macrophage-mediated phagocytosis of tumor cells." (PMID 41019052, 2025). "Through mIF and flow cytometry, we found that tumor intrinsic CD47 overexpression inhibited the infiltration and cytotoxic function of CD8+ T cells, while upregulating the infiltration of myeloid cells compared with the control." (PMID 40523887, 2025). "A synchronized lysis circuit (SLC)-enabled EcN strain has been developed to periodically release CD47 nanobody and PD-L1 nanobody when EcN sense the hypoxic, acid and high-lactate signals in tumor microenvironment." (PMID 41182556, 2025). "Several studies have shown that the combination of CD47 monoclonal antibody (Magrolimab) and PD-1 antibody can significantly reduce tumor size." (PMID 40821806, 2025). "The precise mechanisms involving CD47 in tumor development and progression remain incompletely understood." (PMID 39781344, 2025). "Elevated expression levels of CD47 on healthy cells, notably RBCs, thrombocytes, and PBMCs, pose a concern for on-target off-tumor toxicity." (PMID 40402266, 2025).
tumor (continued). "Hematological malignancies express high levels of CD47 as interactions between CD47 on cancer cells and SIRPα on macrophages inhibit phagocytosis resulting, thus, in tumor immune evasion." (PMID 40369208, 2025). "Mechanistic studies uncovered that Fgl2 KO impaired the immunosuppressive molecule CD47; reconstitution of CD47 expression in Fgl2-KO tumor cells reversed the protection." (PMID 41380903, 2025). "Based on the role of the CD47-SIRPα axis as a regulator of tumor cell fate, a series of molecules that block the CD47-SIRPα axis are currently under clinical development for tumor indications, and in some cases have encouraging clinical outcomes." (PMID 40523887, 2025). "In conclusion, our study demonstrates that the PD-L1 × CD47 aptamer-siRNA chimera represents a novel and effective strategy for selectively depleting tumor-infiltrating Treg cells and enhancing antitumor immunity." (PMID 41402667, 2025). "CD47 is widely expressed in normal human cells; however, SIRPα/CD47 blockade primarily results in tumor cell phagocytosis, as normal human cells lack pro-phagocytic signals." (PMID 41171165, 2025). "Often overexpressed on tumor cells, CD47 interacts with SIRPα on macrophages (a trans interaction) to deliver a “don’t eat me” signal, allowing for tumor cells to evade immune detection." (PMID 40725081, 2025). "Tumor cells frequently overexpress CD47, which, upon binding to SIRPα on the surface of macrophages, transmits a “don't eat me” signal." (PMID 40607254, 2025). "In cancer, many tumor cells overexpress CD47 to avoid phagocytosis, and therapeutic blockade of the CD47–SIRPα axis is being explored to enhance macrophage-mediated clearance." (PMID 41303525, 2025). "Studies have verified that CD47 blockade bolsters anti-tumor responses through macrophage trogocytosis in renal cell carcinoma and diffuse large B cell lymphoma." (PMID 40380196, 2025). "Multiple antibodies targeting CD47 have been developed to prevent SIRPα activation and reprogram TAMs for tumor cell phagocytosis." (PMID 41417432, 2025). "This interaction is particularly important in the context of immune escape in solid tumors, where the overexpression of CD47 on tumor cells helps them evade macrophage-mediated clearance." (PMID 40655153, 2025). "Monoclonal antibodies against CD47 not only enhance macrophage phagocytosis, but also effectively improved adaptive anti-tumor immunity mediated by macrophages." (PMID 40814015, 2025). "Tumor cells often overexpress CD47 on their surfaces, thereby suppressing macrophage function through the CD47-SIRPα pathway, evading phagocytosis, and thus achieving immune escape." (PMID 39861694, 2025). "We determined that HNSCC was the indication with the highest expression and prevalence of CD47, as well as highest density of TAMs, in primary tumor samples." (PMID 41415295, 2025). "Targeting CD47 reduced tumor growth, suggesting improved cancer cell sensitization to the immune system post‐ICP editing." (PMID 39888280, 2025). "Treatment of tumor cells with leucine transporter L-amino acid transporter 2 (LAT2) inhibitors downregulated CD47 expression, thereby enhancing macrophage infiltration and phagocytosis of tumor cells." (PMID 40688069, 2025). "This interaction between CD47 and SIRPα attenuates the phagocytic activity of macrophages, enabling tumor cells to obviate destruction." (PMID 40607254, 2025). "Blocking the CD47/SIRPα axis has been shown to enhance phagocytosis of tumor cells in vitro and promote macrophage-mediated tumor elimination in multiple in vivo tumor models." (PMID 40578556, 2025). "Prevalence was assessed using the percentage of tumor cells that were positive for CD47 membrane scoring above a variety of cutoffs." (PMID 41415295, 2025). "C1QC macrophage signatures correlate with tumor CD47 protein expression in BC and HNSCC samples, suggesting interplay between them." (PMID 41415295, 2025).
tumor (continued). "In contrast, nanovaccines can counteract this chemotherapy‐induced immunosuppression by reducing M2‐like TAMs and enhancing macrophage phagocytosis through the downregulation of CD47 expression in ID8 tumor cells." (PMID 39985265, 2025). "The on-target off-tumor effects of anti-CD47 antibody therapeutics significantly impact the intended functions of the antibodies." (PMID 40578556, 2025). "The SIRPα/CD47 axis represents a crucial innate immune checkpoint that inhibits the phagocytosis of tumor cells by macrophages and monocytes." (PMID 40136470, 2025). "One reason to generate LicMAbs is to retain the therapeutic benefit of blocking the CD47–SIRPα interaction, specifically on tumor cells." (PMID 40402266, 2025). "The local inhibitory checkpoint monoclonal antibody (LicMAb) binds mesothelin (MSLN) with high affinity and simultaneously blocks CD47 on MSLN-expressing tumor cells to inhibit the “don’t eat me” signal." (PMID 40402266, 2025). "Meanwhile, aptamer-siRNA enabled efficient targeted delivery and gene silencing, resulting in robust CD47 knockdown and decreased CD47 surface expression in tumor-infiltrating Treg cells, as confirmed by qPCR and flow cytometry." (PMID 41402667, 2025). "In our study, we propose that IL-8/CXCR2 blockade reduces CD47 expression, which renders tumour cells more vulnerable to macrophage-mediated phagocytosis and increases antitumour immunity." (PMID 41163221, 2025). "Through upregulating CD47 expression on tumor cells, hypoxia prevents macrophage-mediated phagocytosis and activates autophagy in tumor cells, reducing their sensitivity to cytotoxic T lymphocyte (CTL)- and natural killer (NK) cell-mediated cytotoxicity." (PMID 41199316, 2025). "Anti-CD47 enhanced tumor cells sensitivity to radiotherapy in oral squamous cell carcinoma (OSCC) by suppressing cancer stem cell-like phenotype." (PMID 40835598, 2025). "The overexpression of antiphagocytic signals (“don't eat me”) has been correlated with tumor progression, such as signaling involving CD47 and CD24." (PMID 41354057, 2025). "The modified MΦM targets tumor cells and blocks the CD47-SIRPα checkpoint, overcoming immune suppression." (PMID 40225567, 2025). "In the case of PT886, which, in addition to targeting CDLN18.2, also targets CD47, its primary function is to enhance the phagocytosis of tumor cells." (PMID 40862764, 2025). "This engineered nano-bioconjugate system achieved tumor targeting through specific CD47 recognition and facilitated controlled release of anti-SIRPα and anti-CD47 antibodies within the acidic TME." (PMID 40948940, 2025). "Monotherapy with anti-CD47 also resulted in a significant decrease in tumor growth (p=0.048) and an increase in MST (p<0.001) compared to control." (PMID 40529368, 2025). "Leveraging the unique co-expression of PD-L1 and CD47 on tumor-infiltrating Tregs, our aptamer-siRNA chimera achieves cell-type-selective delivery of RNA interference, combining immune checkpoint blockade with gene silencing in a single molecule." (PMID 41402667, 2025). "Preclinical studies in other tumor models have demonstrated that CD47 blockade permits tumor-cell phagocytosis by macrophages with subsequent priming of CD8+ T-cells and suppression of immunosuppressive Tregs." (PMID 40507214, 2025). "Tumor cells overexpress CD47, which binds to SIRPα on myeloid cells, transmitting a “don’t-eat-me” signal to avoid phagocytosis." (PMID 41155938, 2025). "Activation of this pathway directly upregulates the expression of the immunosuppressive molecules PD-L1 and CD47, conferring an immune escape advantage to tumor cells and facilitating tumor growth and metastatic dissemination." (PMID 40865948, 2025). "For instance, tumor-derived cytokines promote macrophage polarization toward a pro-tumor M2 phenotype and suppress phagocytosis through CD47–SIRPα signaling." (PMID 41583469, 2025). "Anti-CD47 antibodies re-enable macrophage-mediated phagocytosis of tumor cells, inducing M1 polarization." (PMID 41562047, 2025).